BRCA1 (BRCA1 DNA repair associated)
Diseases named in the same sentence as BRCA1 in open-access papers (continued):
Sharing a sentence is not in itself a finding about the gene and the disease.
breast cancer (continued). "For example, a study identified frequent BRCA1 germline mutations such as c.1140dupG, c.4136_4137delCT, c.5095C>T, and c.5530delC in Arab breast cancer patients, suggesting potential mutations within this population." (PMID 41294844, 2025). "Our large-scale retrospective multicenter study found that BCT is comparable with mastectomy in terms of oncologic outcomes for patients with breast cancer who carry BRCA1 or BRCA2 pathogenic variants." (PMID 40366658, 2025). "Its HR-deficient (HRD) nature heavily influences treatment strategies for BRCA1-mutated breast cancer." (PMID 39997609, 2025). "Women with a history of breast cancer who are found to carry a BRCA1 or BRCA2 mutation are eligible for insurance coverage for RRM and RRSO." (PMID 41083355, 2025). "Conversely, BRCA1-associated breast cancers are usually estrogen (ER) and progesterone (PR) receptor negative." (PMID 39392573, 2025). "The OlympiA trial evaluated one year of olaparib in high-risk, HER2-negative breast cancer with confirmed BRCA1/2 mutations." (PMID 41514640, 2025). "While an unfortunate diagnosis, as many patients with BRCA1/2 mutations are predisposed to develop multiple tumors, including breast cancer, its detection in ovarian cancer patients is paradoxically linked to a more favorable prognosis." (PMID 40507303, 2025). "RRM has decreased the relative risk of breast cancer in healthy BRCA1 and BRCA2 P/LP variant carriers by 90–95%." (PMID 39858629, 2025). "This highlights that resistance in BRCA1-deficient tumors can arise from both genetic and epigenetic changes, complicating treatment in BRCA1-mutated breast cancers." (PMID 41050078, 2025). "Women with pathogenic BRCA1 or BRCA2 variants have many options to reduce their known high risk of developing breast cancer." (PMID 40599862, 2025). "While most breast cancer cases are sporadic, approximately 10% are attributable to genetic mutations, including those in the breast cancer gene 1 (BRCA1) and breast cancer gene 2 (BRCA2)." (PMID 39997609, 2025). "Inherited gene mutations are found in less than 25% of breast cancer cases, and of these genes, BRCA1 and BRCA2 are the most common cause of hereditary breast cancer." (PMID 40806826, 2025). "It acts against cancers in people with hereditary BRCA1 or BRCA2 mutations including breast cancer and some ovarian and prostate cancers." (PMID 40303990, 2025). "Individuals carrying BRCA1 pathogenetic variant genes have a cumulative risk of developing breast cancer of 72% (95% confidence interval [CI] = 65% to 79%) and 69% in case of BRCA2 genes (95% CI = 61% to 77%)." (PMID 41092066, 2025). "This review focuses on the management of women at high risk for breast cancer, particularly those with pathogenic variants in BRCA1 and BRCA2, who face elevated lifetime risks." (PMID 41083355, 2025). "Apart from ovarian and breast cancers, other BRCA1/2-mutated cancers, including prostate, pancreatic, and small cell lung, have demonstrated clinical efficacy with PARP inhibitor therapy." (PMID 40274769, 2025). "This retrospective multicenter cohort study analyzed patients from 13 institutions in South Korea with primary breast cancer with BRCA1 or BRCA2 pathogenic variants who underwent either BCT or mastectomy from January 2008 through December 2015." (PMID 40366658, 2025). "Breast cancer with the BRCA1/2 gene mutations is thought to have relatively high TMB; however, the number of ILC cases with gBRCA1/2 pathogenic variants is not enough to allow for sufficient consideration." (PMID 40314919, 2025). "In contrast, for the breast cancer data, we use the known mutation information (BRCA1 and BRCA2) but employ K-means clustering to identify gene groups through from the genes' embeddings." (PMID 41542084, 2025). "BRCA1-mutated breast cancer predominantly belongs to the basal-like subtype, as identified through gene expression profiling." (PMID 39997609, 2025).
breast cancer (continued). "To investigate this, we analyzed 27 formalin-fixed paraffin-embedded (FFPE) samples from ovarian and breast cancer patients, all of whom had BRCA1 loss-of-heterozygosity (LOH)." (PMID 40468033, 2025). "In the prospective analysis, higher BMI and adult weight gain were associated with higher risk of postmenopausal breast cancer only for BRCA1 carriers." (PMID 40523654, 2025). "Genetic testing for commonly occurring oncogenes associated with breast cancer—specifically BRCA1 and BRCA2—is progressively becoming a standard procedure in numerous African countries for patients diagnosed with breast cancer." (PMID 40313245, 2025). "The United States and European countries are also focusing their efforts on the diagnosis, surveillance, and prevention of hereditary breast cancer caused by variants in genes other than BRCA1/2." (PMID 39831988, 2025). "In our study, we examined the breast cancer susceptibility associated with two SNPs in BRCA1 (rs386833395) and BRCA2 (rs80359550) through a case-control study involving 335 BC patients and 354 healthy controls." (PMID 40158114, 2025). "Germline mutations in BRCA1 contribute to roughly 20–25% of hereditary breast cancers and about 5–10% of all breast cancer cases." (PMID 41148817, 2025). "Key pathways such as PI3K-Akt signaling, MAPK signaling, and breast cancer are linked with multiple targets including BRCA1, FGFR1, IGF1, AKT1, and EGF, suggesting their potential involvement in breast cancer pathology influenced by PCBs exposure." (PMID 40584614, 2025). "According to a prospective study, the risk of developing breast cancer by age 80 years is 72% for those with a BRCA1 mutation and 69% for those with a BRCA2 mutation." (PMID 40942929, 2025). "From previous Chinese report, we can estimate that family history-positive patients contributed around 28.97% of BRCA1/2 mutations in breast cancer cases." (PMID 40567951, 2025). "We use standard management for unaffected BRCA1/2 mutation carriers, including breast MRI, preventive mastectomy and oophorectomy and, individualized treatment for breast cancer patients with a BRCA1/2 mutation." (PMID 40002208, 2025). "To investigate the potential of PD-1 blockade in suppressing tumor recurrence in an advanced BRCA1-associated breast cancer model, we employed Brca1co/coMMTV-Cre mice that spontaneously develop mammary tumors." (PMID 41208884, 2025). "The tumor suppressor protein BRCA1, significant in breast cancer, is linked to AD, with its dysregulation promoting neuronal cell death." (PMID 40671353, 2025). "The risk of developing ovarian and breast cancers is markedly elevated in individuals with mutations in the BRCA1 gene." (PMID 40141415, 2025). "Three of the fifteen cases with BRCA1/2 mutations developed invasive ipsilateral or contralateral breast cancer, on average 6 years from the diagnosis of DCIS." (PMID 40002208, 2025). "Twenty-four individuals (16.8% [95% CI, 11.1%-23.9%]) with germline testing had PGVs in breast cancer susceptibility genes, including BRCA1 (n = 17 [70.8%]), BRCA2 (n = 5 [20.8%]), PALB2 (n = 1 [4.2%]), and CHEK2 (n = 1 [4.2%])." (PMID 39964682, 2025). "In BRCA1 gene mutation carrier breast cancer cells, the liganded activation of ERs was decreased, and ER alpha also showed decreased expression." (PMID 41514592, 2025).
breast cancer (continued). "Mutations in the BRCA1/2 genes are linked not only to the onset of breast cancer but also have a strong correlation with the development of lung cancer." (PMID 41018110, 2025). "Hyaluronic acid (HA), a key extracellular matrix component, plays a vital role in TME remodeling, while altered breast cancer gene 1 and 2 (BRCA1/2) expression, essential for DNA repair, is linked to cancer aggressiveness." (PMID 41373491, 2025). "Carriers of a single germline mutation in BRCA1 face a heightened risk of developing various cancers, including breast cancer." (PMID 39997609, 2025). "CE-MRI also plays a pivotal role in screening women at high genetic or familial risk of breast cancer, such as those with BRCA1/2 mutations, where its superior sensitivity compared to mammography and ultrasound improves early detection." (PMID 40299402, 2025). "While TNBC accounts for 15–25% of all breast cancer cases, this percentage is significantly higher among BRCA1 mutation carriers." (PMID 39997609, 2025). "In particular, women with germline BRCA1 or BRCA2 mutation carriers are at an increased likelihood of developing breast cancer in their lifetime, with a risk exceeding 70%." (PMID 40155574, 2025). "The other two signals were at BRCA1, coding for a DNA repair protein and associated with increased breast cancer risk, and POLR2A, encoding a subunit of RNA polymerase II." (PMID 40287427, 2025). "BRCA1 mutation carriers have a lifetime risk of approximately 60-70% for developing breast cancer, while those with BRCA2 mutations have a risk of around 45-55%." (PMID 40599862, 2025). "In a genome-wide association study of CNVs in 2500 BRCA1 carriers, 52 gene loci were associated with an increased risk of breast cancer." (PMID 39858629, 2025). "Is breast-conserving treatment (BCT) comparable with mastectomy in terms of oncologic outcomes in patients with breast cancer with BRCA1 or BRCA2 pathogenic variants?" (PMID 40366658, 2025). "The estimated cumulative risks of breast cancer by age 70 in two meta-analyses were 55% to 65% for carriers of BRCA1 pathogenic variants and 45% to 47% for carriers of BRCA2 pathogenic variants." (PMID 39996890, 2025). "BRCA1, among the most well-established breast cancer susceptibility genes 25, is also regulated through histone methylation." (PMID 41048999, 2025). "A prospective cohort analysis evaluated the association between chemoprevention and the risk of breast cancer in unaffected women with BRCA1 or BRCA2 P/LP variants." (PMID 39858629, 2025). "The SUM149PT breast cancer cell line was chosen for this study as a relevant model for studying PARPi activity, since it harbours a hypomorph BRCA1 allele with a mutation in the exon 11 of the gene (2288delT causing partial exon 11 skipping (Δ11q))." (PMID 41459749, 2025). "The germline mutations in breast cancer susceptibility genes BRCA1 and BRCA2 have been linked to genomic instability." (PMID 39860065, 2025). "In the context of Brca1 loss, both human and murine data support the luminal progenitor origin of basal-like breast cancer." (PMID 40676433, 2025). "“Homologous recombination” is the most well-known DDR pathway in breast cancer, particularly in relation to BRCA1 and BRCA2 mutations, which significantly increase the risk of the disease." (PMID 40510149, 2025). "Among 288 women who developed breast cancer during the trial, 19 (6.6%) carried BRCA1 (n = 8) or BRCA2 P/LP variants (n = 11)." (PMID 39858629, 2025). "Basal-like breast cancers account for approximately 15% of all breast cancers and are often seen in patients harbouring a BRCA1 mutation." (PMID 39792888, 2025). "Premenopausal breast cancer risk factors include genetic predispositions, particularly mutations in the BRCA1 and BRCA2 genes, along with lifestyle choices such as obesity, excessive alcohol consumption, and a lack of physical activity." (PMID 40075655, 2025).
breast cancer (continued). "Mutation carriers face a cumulative breast cancer risk by age 70 of approximately 65% for BRCA1 and 45% for BRCA2." (PMID 40075637, 2025). "Risk factors associated with ovarian cancer include advanced age, family history of ovarian or breast cancer, inherited genetic mutations such as BRCA1/2, and reproductive factors such as infertility, endometriosis, and polycystic ovary syndrome." (PMID 41458961, 2025). "In mouse models, denosumab delayed onset, reduced incidence, and attenuated the progression of BRCA1 mutation-driven breast cancer." (PMID 39858629, 2025). "In the current study, the antitumor efficacy of current clinical interventions for TNBC was evaluated using an autochthonous Brca1-mutant mouse model that accurately mimics the characteristics of human BRCA1-deficient mammary tumors." (PMID 41208884, 2025). "Patients with a BRCA1 or BRCA2 gene mutation are at greater risk of developing breast cancer, often at an early age." (PMID 40142718, 2025). "Women with breast cancer, including underrepresented populations, received germline testing to determine P/LP variants in BRCA1 and BRCA2 genes." (PMID 40952741, 2025). "BRCA1/2 mutations occur in approximately 5 to 10% of breast cancer cases and are more prevalent in patients with a family history of breast cancer, younger age at diagnosis, and TNBC." (PMID 40481929, 2025). "An estimated 10% of breast cancer cases are due to an underlying hereditary predisposition, such as a pathogenic/likely‐pathogenic variant in BRCA1 or BRCA2." (PMID 39907309, 2025). "Analyses of cancer risk conferred by pathogenic variants in BRCA1 exon 11 show a reduction in breast cancer risk, but a relative increase in ovarian cancer risk compared to the other regions of the protein." (PMID 40519302, 2025). "RRM decreases the risk of developing breast cancer in carriers of P/LP variants in BRCA1/2 genes by more than 90%." (PMID 40445415, 2025). "Since the discovery of the breast cancer susceptibility gene, BRCA1, which is located on chromosome 17q, significant advances have been made in understanding the structure and function of the BRCA1 protein." (PMID 41155174, 2025). "The detection of BRCA1/2 germline mutations plays a critical role in guiding breast cancer management, particularly in patients with suspected hereditary risks or complex clinical histories." (PMID 40065879, 2025). "The goal of this analysis was to investigate response to chemotherapy and survival outcomes in breast cancer patients with germline BRCA1 or 2 mutations compared with those with wild-type genotypes." (PMID 40405286, 2025). "In our dataset, GPX2 was significantly overexpressed in breast cancer samples with BRCA1 promoter inactivation and identified as a hub gene, suggesting a potential role in tumor progression under BRCA1-deficient conditions." (PMID 40870889, 2025). "The results showed an association between the 86-SNV PRS and breast cancer risk for each of the carrier populations: BRCA1 (OR 1.20; 95% CI 1.10–1.32), BRCA2 (OR 1.23; 95% CI 1.12–1.34), ATM (OR 1.37; 95% CI 1.21–1.55), and PALB2 (OR 1.34; 95% CI 1.16–1.55)." (PMID 39858629, 2025). "Approximately 8–10% of breast cancer cases are attributed to hereditary mutations, half of which are related to BRCA1 and BRCA28,9." (PMID 40531772, 2025). "LINC00323 has also been implicated in controlling cell growth and death in breast cancer, with its expression serving as a potential indicator of BRCA1’s functional state and patient prognosis." (PMID 39997609, 2025).
breast cancer (continued). "In another study, carriers of impaired BRCA1 genes had a cumulative risk of breast cancer of 72% by the age of 80, and for BRCA2, the corresponding risk was 69%." (PMID 40361383, 2025). "BRCA1 mutations are more commonly associated with the basal-like (triple-negative) breast cancer subtype, which is known for its poor prognosis and high recurrence rates." (PMID 40149262, 2025). "The average cumulative risk of developing breast cancer by the age of 80 years is 72% [95%CI = 65–79] for BRCA1 carriers and 69% [95%CI = 61–77%] for BRCA2 GPV carriers, compared to a lifetime risk of 12.9% in the general population." (PMID 40427184, 2025). "BRCA1/2 mutation carriers with a family history of breast cancer were found to have a higher risk of breast cancer than those who report no breast cancer in their relatives." (PMID 40002208, 2025). "Beyond clinicopathological factors, genetic profiling—especially BRCA1/2 germline mutation status—plays an increasingly important role in personalized breast cancer treatment." (PMID 41140671, 2025). "Denosumab, a monoclonal antibody that tackles receptor activator of nuclear factor kappa B (RANK-RANKL), is promising in preventing breast cancer in healthy carriers of pathogenic BRCA1 variants." (PMID 40599862, 2025). "Breast cancer with a germline BRCA1/2 mutation (gBRCAm) is sensitive to DNA-damaging therapies, such as platinum therapies and poly (ADP-ribose) polymerase (PARP) inhibitors." (PMID 40507226, 2025). "It is important to note another study that assessed the association of low zinc levels and BRCA1 mutations with the risk of developing breast cancer and ovarian cancer." (PMID 40429927, 2025). "Assuming a 3.2% positivity rate for family history, family history-positive individuals contributed to 83.44% of BRCA1/2 mutations in breast cancer cases, approximately 2.88 times higher." (PMID 40567951, 2025). "For example, germline mutations in the BRCA1/2 genes, which are strongly associated with breast cancer, have also been found to be linked to a slightly increased risk of colorectal cancer." (PMID 41378290, 2025). "In men, several factors significantly increase the risk of breast cancer, including BRCA2 and BRCA1 mutations, advanced age, Klinefelter syndrome, elevated estrogen levels, radiation exposure, and a family history of breast cancer." (PMID 40800071, 2025). "Numerous strategies are under investigation to address the persistent gap in primary immunoprevention for breast cancer, particularly in women at high genetic risk, such as BRCA1 mutation carriers." (PMID 41300964, 2025). "The GEN1 gene is implicated in DNA damage repair, as are several high- or moderate-risk breast cancer susceptibility genes, i.e., BRCA1, BRCA2, PALB2, CHEK2, ATM, and BRIP1." (PMID 40649769, 2025). "A class of medications known as PARP inhibitors (PARPis) is mainly used to treat breast cancers, especially those with BRCA1 and BRCA2 mutations." (PMID 40141415, 2025). "Breast cancer is the most common cancer in Japanese women, and approximately 10% of these cancers are thought to be hereditary, with 4%–5% (about half of hereditary breast cancers) reported to be caused by BRCA1 or BRCA2 variants." (PMID 39831988, 2025). "Here, we identified a homozygous missense variant (c.2312T > C:p.Leu771Ser) in BRCA1 as the likely cause of breast cancer among selected patients, reinforcing the need to integrate genetic screening into clinical care for high-risk populations." (PMID 40904409, 2025). "The breast cancer-associated gene 1 (BRCA1) is a well-known tumor suppressor gene, whose germline mutation is responsible for 20–30% of hereditary breast cancers and ~2–4% of total breast cancer cases." (PMID 41318657, 2025). "Many genetic variants only cause a slight increase in radiation sensitivity such as heterozygous pathogenic variants in the breast cancer risk genes BRCA1 and BRCA2." (PMID 41210219, 2025).